TLR4 (toll like receptor 4)
Diseases named in the same sentence as TLR4 in open-access papers (continued):
Sharing a sentence is not in itself a finding about the gene and the disease.
infection (continued). "Especially, the TLR4 gene polymorphisms should be compared between persistence infection and spontaneous viral clearance due to the fact that uncommon cases are self-limitation which occurs approximately 20%." (PMID 30765614, 2019). "We found that fetal Tlr4 and Ifnar1 genes show protective effects during the course of infection, opposing the pathogenic action of the maternal counterparts." (PMID 29440369, 2018). "Recent studies have focused on TLR2 and TLR4, as these TLRs recognize the widest range of microbial components involved in PD-associated infections and are also the main TLRs involved in sterile inflammatory responses." (PMID 30538643, 2018). "It has been suggested that the interaction of PLY with TLR4 is critically involved in the innate immune response to S. pneumoniae: TLR4-mutant mice were more susceptible to lethal infection with PLY-positive pneumococci." (PMID 30100903, 2018). "Described in the udder, the TLR4 expression strongly increases in infection caused by Staphylococcus Aureus and E. coli." (PMID 29642663, 2018). "The attenuated course of infection observed in TLR4−/− mice implicated downstream mediators of the TLR4 pathway as important in the robust, early response in eyes infected with B. cereus." (PMID 29661181, 2018). "There is a report that MRP14 induces the secretion of TNFα, IL-1β and IL-6 dependent on TLR4, and it is also reported that these inflammatory cytokines can be associated with the pathology during infection with P. berghei." (PMID 29902248, 2018). "A separate study showed that macrophage Ifnb1 expression upon infection with the M. tuberculosis clinical isolate 1254 was equivalent between wild-type cells and macrophages deficient in Tlr4, Tlr2, Tirap, Myd88, or Trif." (PMID 29230217, 2017). "This has been somewhat surprising, because in a previous study the authors reported that TLR4-defective mice (C3H/HeJ strain) were more susceptible than wild-type mice to intradermal infection with LVS." (PMID 29085810, 2017). "In the TLR3/TLR4-associated subnetwork from the chronic stage of infection, JUN has the highest node degree and betweenness values." (PMID 28487699, 2017). "After infection of TLR4-deficient mice, the total cell counts were significantly lower than those in wild-type mice, which indicates that TLR4 expressed on cell surface is needed for inflammatory cell activation." (PMID 28376744, 2017). "Again, adding of CLI-095 reduced the rates of infection at both 24 h and 96 h further confirming the role of TLR4-dependent differentiation in the susceptibility of THP-1 cells to EBOV-infection." (PMID 28542576, 2017). "In this study, Module 3 extracted from the TLR3/TLR4-associated subnetwork at the acute stage of infection contains five nodes that play crucial roles in My88-independent TRIF-dependent TLR signaling." (PMID 28487699, 2017). "Tolerization, which is crucial for dampening a recurrent inflammatory insult and protects the host to fatal infection (i.e, during sceptic shock), is associated with repression of TLR4-mediated signaling and reduced TLR4 surface expression." (PMID 27628304, 2017). "Surprisingly, TLR4 was partially implicated in IFN-β expression by DCs following infection with both the ST7 strain SC84 and the ST1 strain P1/7 (p < 0.05), which corresponded to a reduction of approximately 15%." (PMID 28894449, 2017). "When the main causes of TRM were analyzed according to the TLR4 +3725G>C genotype, the donor TLR4 +3725G/G genotype was associated with a significantly lower incidence of fatal infections than other genotypes (P=0.047)." (PMID 28484092, 2017). "Previous studies support the notion of targeting TLR4 to prevent infection-associated preterm birth." (PMID 27819333, 2016). "An association between TLR4 genetic polymorphism and infection susceptibility has been reported in patients with and without cirrhosis." (PMID 27861595, 2016).
infection (continued). "TLR4 signaling is a double-edged sword that protects the host from infection but also causes tissue damage, and therefore requires careful regulation and fine tuning." (PMID 26189595, 2015). "Of note, TLR4−∕− mice received one-fifth Y. enterocolitica dose of WT experiments due to their higher susceptibility to the infection." (PMID 26793623, 2015). "TLR-4 genetic variants have been mainly investigated in relation to infection susceptibility, and few data have been reported regarding their correlation with aGvHD." (PMID 25973432, 2015). "Comparison of induced infections in C57BL10/ScN mice carrying a null mutation in TLR4 to TLR4-competent C57BL10/ScSn mice showed high parasite loads in the C57BL10/ScN mice." (PMID 26107286, 2015). "Similar to our findings with L. amazonensis, hepcidin production and decrease cell surface-associated Fpn1 triggered by infection with Pseudomonas aeruginosa require TLR4." (PMID 24497831, 2014). "The importance of TLR4 during infection with Nm is reflected by the close association of disease severity and inflammatory response with the level of LPS in plasma and CSF." (PMID 25347003, 2014). "C3H/HeJ mouse strain which is known be TLR4 deficient showed to survive longer to the infection comparing to BALB/cJ and C57BL/6 J, but similar to DBA/2 J." (PMID 25283706, 2014). "While the inflammatory response is essential for clearing pathogenic infection, it must be tightly regulated–a role that is fulfilled in part by miR-146a in response to TLR4 activation." (PMID 24699816, 2014). "In a model of inflammatory pain caused by infection, injection in the mice paw of lipopolysaccharide (LPS), a Toll-like receptor 4 (TLR4) agonist, produces mechanical hyperalgesia." (PMID 24595131, 2014). "Toll-like receptor TLR2 and TLR4 have also been found to be necessary for effective innate immune control of infection; however, the immunological responses underlying the differences between infection of reservoir and incidental hosts remain a mystery." (PMID 25437801, 2014). "Loss of control of infection leads to enhanced but ineffective TLR4-mediated inflammatory responses that prolong disease symptoms." (PMID 22724018, 2012). "Similar to the results described for the spleen, systemic spread of the organism to the liver is delayed in TLR4−/− and MyD88−/− mice, and is associated with a corresponding delay in the clearance of infection." (PMID 22973560, 2012). "Infection by Cryptosporidium parvum activates TLR4/NF-κB signaling and increases miR-27b expression, causing a suppression of KSRP in infected host epithelial cells." (PMID 22615562, 2012). "Herein, we establish how temperature dependent shifts in the lipid A of Yersinia pestis LPS that differentially impact recognition by mouse versus human TLR4/MD-2 dictate infection susceptibility." (PMID 23071439, 2012). "Reciprocally, administration of TLR4 agonists augments host defense against Y. pestis further highlighting the potential importance shifts in TLR4 recognition play in infection susceptibility." (PMID 23071439, 2012). "This is the first study to demonstrate a role for TLR4 in infection associated with C. difficile and suggests an important role for SLPs in the generation of the immune response necessary for clearance of this bacterium." (PMID 21738466, 2011). "Infection with Cryptococcus neoformans results in an upregulation of CD95L on 'glucuronoxylomannan'/'toll-like receptor-4' (GXM/TLR-4)-triggered macrophages, associated with increased apoptotic T cell death in activated cells." (PMID 21477291, 2011). "As conventional housed mice are not susceptible to C. difficile infection, we evaluated if the intestinal alterations in TLR4−/− and MyD88−/− mice rendered these mice innately more susceptible to infection." (PMID 21738466, 2011).
infection (continued). "In the first part of this study we were able to show an association between the risk of severe infections and a combination of genetic variants in sequential molecules of the LPS-sensor consisting of TLR4 and its adaptor TIRAP/Mal." (PMID 20525286, 2010). "We show that mice of either B10 or B6 genetic background with TLR4 deficiency presented significantly elevated parasite numbers in the blood compared to their WT controls after in vivo infection with T. cruzi." (PMID 20442858, 2010). "Compared to symptomatic patients and healthy controls, ABU patients had fewer genotype patterns, and their promoter sequence variants reduced TLR4 expression in response to infection." (PMID 20505764, 2010). "RSV F protein causes TLR4-mediated NF-κB activation during the early infection stages of infection that is dependent upon virus replication." (PMID 20672047, 2010). "The loss of TLR4 has major repercussions for host defense, including impaired resolution of infection." (PMID 20657826, 2010). "We further monitored the mortality after infection and found that TLR4-deficiency in both B10 and B6 backgrounds results in higher lethality." (PMID 20442858, 2010). "As with the in vitro results obtained with macrophage cultures, the inhibition of NO production during in vivo infection made WT and Tlr4−/− mice equally susceptible, as measured by mortality and parasite levels in the blood." (PMID 20442858, 2010). "This has been a somewhat surprising finding since F. tularensis is a Gram-negative bacterium and because a previous study reported that TLR4-defective mice (C3H/HeJ strain) were more susceptible to intradermal infection with LVS." (PMID 19936231, 2009). "Our laboratory reported a protective role of TLR4 during infection of the lower respiratory tract by S. pneumoniae, demonstrating an enhanced growth of bacteria in lungs of TLR4-deficient mice." (PMID 17711480, 2008). "On the contrary, the d120 infection was associated with lowered TLR4 mRNA expression level at 24 h p.i. when compared to its parental virus HSV-1 (KOS)-infected cells (1 moi, P = 0.024 and 5 moi, P = 0.024)." (PMID 19025601, 2008). "One of these characteristics is the modulation of TLR4 signaling under the dual pressure of protecting the host from pathogenic infections and coexistence with the myriad commensal organisms." (PMID 17389921, 2007). "During systemic infections, LPS ligation to the hepatic Toll-like receptor-4 complex induces the production of a wide variety of hepatic acute phase proteins that are involved in the host response to infection and limit the associated inflammatory process." (PMID 17134499, 2006). "Despite an abundance of in vitro data regarding the recognition of mycobacterial structures by TLR2 and TLR4, knock-out mice deficient for these receptors display remarkably little enhanced susceptibility to infection with M. tuberculosis." (PMID 16322770, 2005). "We generated myd88- or tlr4-deficient T24/83 cells to explore whether the infection triggers cytokine secretion via this signaling cascade." (PMID 41310197, 2025). "Finally, in a UTI model, our laboratory found that tlr4 mutant C3H/HeJ mice were more susceptible to infection than WT C3H/HeN mice." (PMID 40817088, 2025). "To determine whether the reduced expression of tlr2 and tlr4 following infection of zebrafish with the Δhcp2 strain is associated with PGN and LPS, we quantitatively analyzed the LPS and PGN content of V. alginolyticus." (PMID 41230815, 2025). "Beyond TLR4, other genetic factors also contribute to infection risk." (PMID 41550938, 2025). "Since resistance to acute lethal infection with L. interrogans was associated with a functional tlr4 and C3H/HeJ is hyporesponsive to L. interrogans atypical LPS, there are valid concerns that this mouse model does not recapitulate a competent immune response to this spirochete." (PMID 40445994, 2025).
infection (continued). "We used C3H/HeJ mice, a strain known for mutations in the TLR4 gene that shows more pronounced LD symptoms, and carried out experiments to determine the impact of both short-term (2–4 weeks) and long-term (8–16 weeks) infection on host and pathogens." (PMID 40793757, 2025). "First, TLR4 is a crucial component of the host immune system; excessive TLR4 inhibition may lead to broad immune system suppression and an increased risk of infection." (PMID 41395459, 2025). "Notably, the TLR4-MyD88-NF-κB signaling pathway serves as an critical nexus associated with hepatic tissue infection, injury, and inflammation." (PMID 39776579, 2024). "Furthermore, we controlled for priming effects by interferon-gamma (IFNγ) treatment before infection and included an LPS control, allowing to identify effects caused by bacterial activation of Toll-like receptor 4 (TLR4)." (PMID 39366977, 2024). "One of the initial reactions to infection involves the binding of pathogen-associated molecular patterns (PAMPS) such as lipopolysaccharides (LPS) to pattern recognition receptors (PRRs) such as toll-like receptor 4 (TLR4)." (PMID 39272988, 2024). "TLR4 in lung tissue may be activated by risk factors such as cigarette smoking, inhaled polluted air, and infection of bacteria and viruses." (PMID 39139567, 2024). "In vivo infection experiments have demonstrated that CD mucosa-associated E. coli killing by macrophages could be inhibited by microbial mannan in a TLR4 and MyD88-dependent manner." (PMID 37311220, 2023). "Interestingly, we also observed a reduced expression of Toll-like receptor 4 (TLR4) in monocytes from KCASP1Tg mice, potentially predisposing these animals to heightened infection risks and associated complications." (PMID 38203647, 2023). "However, we did observe a decreased frequency of IDO-1+ M-MDSCs at 72 h post infection in TLR4-deficient mice compared to WT controls." (PMID 37524886, 2023). "We conclude that the evolutionary advantage of TLR4 improved defence against infections might come to the cost of increased risk for SARS-CoV-2 associated hyperinflammation and death, constituting a model of pleiotropic antagonism." (PMID 38034686, 2023). "However, no studies on T2DM have been conducted in the Saudi population, although there is an association between infection, the TLR4 gene, and T2DM." (PMID 37830554, 2023). "Likewise, TLR-4 categorized as a pathogenic infection indicator, has been shown to be up-regulated during an E. tenella infection." (PMID 36230268, 2022). "Also, in vitro analysis indicates that RAGE has a higher affinity with S100A8/A9 than TLR4, whereby the former interaction is linked with inflammation-mediated carcinogenesis and the latter with autoimmune disorders and infection." (PMID 34980167, 2022). "A recent study showed that in C3H/HeJ mice deficient for TLR4, infection with the pathogenic L. interrogans Copenhageni strain Fiocruz L1-130 increased the number of DCs in spleens, showing that in vivo in mice, leptospires can trigger DC activation independently of TLR4." (PMID 35812397, 2022). "The tlr4 −/− knockout mice infected with this fungal species showed high levels of fungal burden and deficient cytokine production after 14 days of infection when compared with wild-type mice, indicating that this receptor is also relevant for this pathogen control." (PMID 37746241, 2022). "These patients showed no obvious association with the gram status of the underlying infection, as one might have suspected, and can thus far only be identified by measuring the activation of TLR4." (PMID 36230982, 2022). "Tlr4 also has a known point mutation linked to STm susceptibility, but none of the CC founder strains carry a mutation in this gene, making it impossible to verify the effect of this mutation on STm infection using CC mice." (PMID 35417454, 2022).
infection (continued). "On the other hand, HPV 16/18 infection was shown to be associated with TLR4 rs4986790 and rs1927911, which may somewhat indicate its negative role in the development of HCV-related HCC." (PMID 35267595, 2022). "The increased expression of TLR4 after Mollicutes infections may be associated with the induction of autophagy in the cells." (PMID 36296238, 2022). "Additionally, we reported reduced Neu1 during L. donovani-infection enhanced sialylation on TLR4 preventing its association with MyD88 resulting in an inappropriate cellular activation." (PMID 33763070, 2021). "Moreover, the association between infections and TLR4 showed a borderline effect in all patients (p = 0.051) and was nominally significant in the preemptive treatment group (p = 0.038)." (PMID 33861738, 2021). "Moreover, both TLR2 and TLR4 are implicated in recognition of damage-associated molecular patterns (DAMPs) released from necrosis-causing infections, including heat shock proteins (HSPs), high mobility group box-1 (HMGB1) protein, and oxidized phospholipids." (PMID 33498715, 2021). "Moreover, these cells also demonstrated enhanced TLR4-MyD88 and upregulated TLR4-TRIF association in the co-transfected cells following infection." (PMID 33763070, 2021). "In summary, our findings demonstrate that TLR4 is an important mediator of disease pathogenesis in C3H mice infected with VEEV TC-83 as TLR4mut mice are less susceptible to disease during VEEV TC-83 infection." (PMID 33487119, 2021). "TLR4 is an innate immune receptor on the cell surface that recognizes pathogen-associated molecular patterns (PAMPs) including viral proteins and triggers the production of type I interferons and proinflammatory cytokines to combat infection." (PMID 33505220, 2021). "However, the exact mechanism of TLR2 or TLR4 polymorphisms in the pathogenesis of C. difficile colonization or infection warrants further examination." (PMID 34322122, 2021). "TLR4-/- mice were more susceptible to intranasal A. baumannii infection than wild-type mice, with higher tissue bacterial burdens and more persistent infection." (PMID 33042864, 2020). "Of note, glucocorticoid can attenuate the host immunity by inhibiting toll-like receptor 4 (TLR4) signaling and T cell activation, which may cause the secondary infection of other pathogens." (PMID 32733842, 2020). "Similarly, during the early stages of infection of GF zebrafish with Vibrio anguillarum, the expression of genes encoding interleukin 1 beta (IL-1β), toll-like receptor 4 (TLR4), NF-κB, and transferrin (TRF) decreased significantly." (PMID 33147801, 2020). "Moreover; significant association between TLR2 polymorphisms, TLR4 Arg753Gln polymorphisms and risk of severe infections in AML patients was documented." (PMID 33247673, 2020). "Differences in pathology between TLR4-competent and TLR4-deficient mutant mice were evident; thus, we investigated whether dissimilarities in the bacterial burden occur during the infection phase." (PMID 32403973, 2020). "This relatively specific mechanism of action may overcome the infection predisposition as a limitation for the use of TLR4 inhibitors as a therapeutic target in IIM." (PMID 32164729, 2020). "In addition to DAMPs, other effector molecules released from fetal or placental tissues under sterile or infection‐associated conditions stimulate TLR4‐dependent pathways to promote parturition and preterm birth." (PMID 32313651, 2020). "We expected that infection with Mtb K might reveal the role of TLR4 because the highly virulent Mtb K strain is associated with TB outbreaks, inducing TB progression more efficiently than the laboratory strain H37Rv." (PMID 32403973, 2020).